MAFK (MAF bZIP transcription factor K)
Description:
Since they lack a putative transactivation domain, the small Mafs behave as transcriptional repressors when they dimerize among themselves. However, they act as transcriptional activators by dimerizing with other (usually larger) basic-zipper proteins, such as NFE2, NFE2L1/NRF1, NFE2L2/NRF2 and NFE2L3/NRF3, and recruiting them to specific DNA-binding sites. Small Maf proteins heterodimerize with Fos and may act as competitive repressors of the NF-E2 transcription factor.
Synonyms: P18; NFE2U
Tractability: Small molecule: a high-quality ligand is known. PROTAC: UniProt records ubiquitination sites on it; ubiquitination databases record sites on it; its protein half-life has been measured; a small molecule that binds it is known.
Target class: Transcription factor
Safety:
Unwanted effects reported when the protein is acted on. In parentheses: how it was acted on, where the effect was seen, and who reports it.
liver injury (source: ClinPGx)
Gene: Protein-coding gene on chromosome 7 (1,530,702 to 1,543,049, forward strand). Ensembl gene ENSG00000198517.
Subcellular location: Nucleus
Subcellular location (Human Protein Atlas): Nucleoplasm
Pathways (Reactome):
Cellular responses to stimuli: Heme signaling; NFE2L2 regulating ER-stress associated genes; NFE2L2 regulating MDR associated enzymes; NFE2L2 regulating anti-oxidant/detoxification enzymes; NFE2L2 regulating inflammation associated genes; NFE2L2 regulating tumorigenic genes; Nuclear events mediated by NFE2L2; Regulation of BACH1 activity; Regulation of HMOX1 expression and activity; Regulation of NFE2L2 gene expression
Chromatin organization: CHD6, CHD7, CHD8, CHD9 subfamily
Hemostasis: Factors involved in megakaryocyte development and platelet production
Gene Ontology:
Molecular function: DNA-binding transcription repressor activity, RNA polymerase II-specific; protein binding; sequence-specific DNA binding; DNA-binding transcription factor activity; DNA-binding transcription factor activity, RNA polymerase II-specific; RNA polymerase II cis-regulatory region sequence-specific DNA binding; transcription cis-regulatory region binding; DNA binding
Biological process: negative regulation of transcription by RNA polymerase II; regulation of transcription by RNA polymerase II; regulation of DNA-templated transcription
Cellular component: nucleoplasm; chromatin; nucleus
Genetic constraint (gnomAD): Loss-of-function variants: 2 observed, 6.47 expected, observed/expected ratio (o/e) 0.31, 90% interval 0.12 to 0.97. That is too few expected variants to judge how well the gene tolerates losing a copy. Missense variants: 207 observed, 209.13 expected, observed/expected ratio (o/e) 0.99, 90% interval 0.88 to 1.11. Synonymous variants: 110 observed, 94.07 expected, observed/expected ratio (o/e) 1.17, 90% interval 1 to 1.37.
Homologues: Orthologues: chimpanzee MAFK (99% identical), macaque MAFK (98% identical), mouse Mafk (98% identical), rat Mafk (97% identical), dog MAFK (96% identical), guinea pig MAFK (95% identical), pig MAFK (94% identical), tropical clawed frog mafk (90% identical), zebrafish mafk (83% identical), Drosophila melanogaster maf-S (38% identical), Drosophila melanogaster tj (37% identical), Caenorhabditis elegans maf-1 (31% identical). Paralogues in human: MAFG (76% identical), MAFF (67% identical), MAF (47% identical), MAFB (46% identical), MAFA (42% identical), NRL (37% identical).
Diseases named in the same sentence as MAFK in open-access papers:
MAFK is named in the same sentence as 38 diseases in open-access papers, as found by Europe PMC text mining. Sharing a sentence is not in itself a finding about the gene and the disease. The quoted sentences say what the papers report.
breast carcinoma (4 papers, 2013 to 2023). "SSX3, the most stably expressed in “B” is a prognostic predictor for pancreatic ductal adenocarcinoma, while MAFK, the most variably expressed gene in “B”, appears responsible for the induction of breast cancer." (PMID 34209090, 2021). "MAFK overexpression could induce epithelial-mesenchymal transition phenotypes of breast cancer cells while facilitating tumor formation." (PMID 37838657, 2023). "Endogenous MafK and Bach1 also suppressed HO-1 in breast cancer cells." (PMID 23737527, 2013). "It was revealed that MAFK, a MAF family member, was abundant in human TNBC and aggressive mouse mammary tumor cell lines." (PMID 37838657, 2023). "MafK Induces EMT and promotes tumor invasion in vivo in breast cancer." (PMID 37491302, 2023).
fibrosarcoma (4 papers, 2017 to 2023). A malignant mesenchymal fibroblastic neoplasm affecting the soft tissue and bone. "The relative mRNA expression levels of selenoprotein W (SELENOW), SEPP1, masculoaponeurotic fibrosarcoma K (MafK), CAT, SOD1, SOD2, and NAD (P)H: quinone oxidoreductase 1 (NQO1) genes in TN + SeNPs-AOS group were higher than TN group (p < 0.05)." (PMID 38001826, 2023). "The small musculoaponeurotic fibrosarcoma (sMaf) proteins MafF, MafG, and MafK are basic region leucine zipper- (bZIP-) type transcription factors and display tissue- or stimulus-specific expression patterns." (PMID 33488846, 2020).
triple-negative breast carcinoma (4 papers, 2020 to 2023). An invasive breast carcinoma which is negative for expression of estrogen receptor (ER), progesterone receptor (PR), and human epidermal growth factor receptor 2 (HER2). "Similarly, MAFK is also highly expressed in triple-negative breast cancer; the upregulation of MAFK influences a tumour’s susceptibility to salmonella mucosal infection." (PMID 37371607, 2023). "Moreover, enforced MafK expression is related to poor prognosis in triple-negative breast cancer patients." (PMID 36750911, 2023). "Similarly, MAFK was also reported to promote the progression of triple-negative breast cancer, in which MAFK notably induced epithelial-mesenchymal transition (EMT) and tumor invasion by regulating the targeted gene GPNMB40." (PMID 35449156, 2022). "Overexpression of MAFK induced epithelial-mesenchymal transition (EMT) phenotypes and promoted triple-negative breast cancer formation and invasion in mice." (PMID 33490259, 2020).
acute myeloid leukemia (2 papers, 2013 to 2022). Acute myeloid leukemia (AML) is a group of neoplasms arising from precursor cells committed to the myeloid cell-line differentiation. "Studies have shown that MAFK is closely associated with pancreatic cancer, acute myeloid leukemia, and osteosarcoma, implying it is a potentially new therapeutic targets for different cancers." (PMID 35756490, 2022).
colorectal cancer (2 papers, 2022 to 2025). A primary or metastatic malignant neoplasm that affects the colon or rectum. "We successfully knocked down OTX2, RUNX1, MAZ,s and MAFK in HCT116 colorectal cancer cells, respectively." (PMID 35712778, 2022).
hepatocellular carcinoma (2 papers, 2017 to 2022). A malignant tumor that arises from hepatocytes. "Interestingly, enriched MafK signals at the MARE-1 site were found in lung A549 lung and HepG2 liver carcinoma cells, implying potential regulation of the AHSP gene by other CNC-bZIP family members." (PMID 35092867, 2022).
asthma (1 paper, 2024). "MAFK has not been previously associated with asthma or autism." (PMID 39247132, 2024).
colon inflammation (1 paper, 2022). "MafK Tg mice had increased levels of the inflammatory enzymes Cox-2 and iNOS, both of which have been linked to colon inflammation and cancer." (PMID 35260530, 2022). "WT and MafK Tg mice were infected with Salmonella for 2 days to explain the involvement of MafK in intestinal colitis limitation by evaluated the production of proinflammatory mediators in the ceca." (PMID 35260530, 2022). "We found that apoptosis induced by MafK was enhanced in epithelial cells and contributed to the increased sensitivity to Salmonella-induced colitis and uncontrollable bacteria dissemination in MafK Tg mice." (PMID 35260530, 2022).
COVID-19 (1 paper, 2021). A disease caused by infection with severe acute respiratory syndrome coronavirus 2. "Interestingly, although with a lesser intensity, the upregulation of AREG, MAFG, MAFK, BCL6 and IL10 still persisted in monocytes of post-COVID-19 subjects." (PMID 34572439, 2021).
Immune deficiency (1 paper, 2019). "Immune deficiency may be related to several genes, especially Platelet-derived growth factor alpha (PDGFalpha), caspase recruitment domain 11 (CARD11), N-acetylglucosaminyltransferase lunatic fringe (LFNG), MafK, and G protein-coupled estrogen receptor 1 (GPER-1)." (PMID 31474980, 2019).
influenza (1 paper, 2019). An acute viral infection of the respiratory tract, occurring in isolated cases, in epidemics, or in pandemics; it is caused by serologically different strains of viruses (influenzaviruses) designated A, B, and C, has a 3-day incubation period, and usually lasts for 3 to 10 days. "We confirmed gene array data using RT-qPCR analyses of c-Maf, MafF, and MafK expression in sorted NK cells from influenza-infected WT and Ebi3−/− mice." (PMID 30899058, 2019).
leukemia (1 paper, 2020). A malignant (clonal) hematologic disorder, involving hematopoietic stem cells and characterized by the presence of primitive or atypical myeloid or lymphoid cells in the bone marrow and the blood. "The IMSGC GWAS and dSNP rs62420820 shows allele-specific TF binding differences for MafF and MafK in the leukemia cell line K562." (PMID 32012148, 2020).
liver fibrosis (1 paper, 2022). "Considering the link between hepatocyte lipotoxicity and liver fibrosis in NASH prognosis, we subsequently defined the association between TCF4- and MAFK-sensitive genes and human NASH at different stages of fibrosis." (PMID 35798791, 2022). "Moreover, in the context of lipotoxicity, some MAFK and TCF4 target genes were to the corresponding differentially regulated transcripts in human liver fibrosis." (PMID 35798791, 2022).
lung carcinoma (1 paper, 2023). "MAFK could also serve as a cancer essential gene in several lung cancer cell lines from the Depmap dataset." (PMID 37491302, 2023).
porphyria (1 paper, 2014). Porphyria is a group of diseases in which substances called porphyrins build up, negatively affecting the skin or nervous system. "Specifically, in conditions of heme-deficiency such as porphyria, the Bach1b-MafK heterodimer occupies the MARE sites of the genes encoding pancreatic zymogens and represses their expression." (PMID 24652768, 2014). "In conditions of heme deficiency, such as porphyria, the repressive Bach1b-MafK heterodimer prevails; and through its binding to Bach1b, hemin facilitates the formation of the activating Nrf2a-MafK heterodimer, restoring the expression of these zymogens in porphyria." (PMID 24652768, 2014).
Salmonella Infections (1 paper, 2022). Infections with bacteria of the genus SALMONELLA. "Our studies showed only a mild decrease in the expression of claudin 3 in naïve MafK Tg mice, which might have contributed to the increased susceptibility to Salmonella infection." (PMID 35260530, 2022). "Although there was a decrease in mucin 2 expression following Salmonella infection in MafK Tg mice, it might have been caused by overt tissue damage leading to an increased loss of goblet cells." (PMID 35260530, 2022). "Comparatively, when compared to WT mice, TNF-α, IL-6, and INF-γ of MafK Tg mice were increased significantly following Salmonella infection for 2 days in the colon." (PMID 35260530, 2022). "In response to the Salmonella infection, the levels of p65 in the nucleus of MafK-overexpressing Caco-2 cells were significant increased than those in control cells." (PMID 35260530, 2022). "After Salmonella infection in MafK-overexpressing Caco-2 cells and control cells, the levels of p65 in the cytoplasm were not different." (PMID 35260530, 2022). "Following Salmonella infection, MafK induces epithelial cells to progress to quicker apoptosis, which results in a fragile intestinal barrier that is more easily penetrated by microbes." (PMID 35260530, 2022). "WT and MafK Tg mice were oral administration with streptomycin before Salmonella infection." (PMID 35260530, 2022). "Similar to the TUNEL staining results, cleaved caspase-3 was higher in cecum of MafK Tg mice than WT mice following Salmonella infection for 2 days; however, this phenomenon might have been cause by overt tissue damage." (PMID 35260530, 2022). "MafK Tg mice had more apoptotic cells than WT mice following Salmonella infection for 6 h." (PMID 35260530, 2022). "Collectively, these data suggested that the failure of MafK Tg mice to protect against Salmonella infection might result from the fragile tight junction barrier function." (PMID 35260530, 2022).
ulcerative colitis (1 paper, 2022). An inflammatory bowel disease involving the mucosal surface of the large intestine and rectum. "A recent report showed that Musculoaponeurotic fibrosarcoma K (MafK) expression is increased in patients that have ulcerative colitis (UC)." (PMID 35260530, 2022).
cancer (13 papers, 2018 to 2024). A tumor composed of atypical neoplastic, often pleomorphic cells that invade other tissues. "The activity of GATA‐family and MEF2C TF was upregulated in luminal cancer cells, while that of the ATF (BATF/MAFK/MAFF/BACH1) TF was upregulated in basal cancer cells." (PMID 38582099, 2024). "The results demonstrated that MAFK was highly expressed in cancer cell lines at the RNA and protein level, although the expression levels varied across cell lines." (PMID 37491302, 2023). "Although the function of NFE2L1/2 and its binding partners (MafG, MafF, and MafK) to form heterodimers in cancer has been extensively studied, their distinguishing roles in the regulation of PD-L1 and immune evasion are poorly understood." (PMID 37985752, 2023). "Some genes played well-prognostic factors in cancers, for example, MAFK in KICH, MAPK3 in PCPG and MESC, NRF2 in UVM, and PIK3CA in KIRC." (PMID 35242279, 2022). "MAF bZIP transcription factor K (MAFK), an important transcription factor of the MAF family, is associated with epithelial–mesenchymal transition and malignant progression in different cancers." (PMID 33968141, 2021). "Interestingly, in region “B”, both the most stably expressed (SSX3) and the most unstably expressed (MAFK) genes have recognized roles in various forms of cancers." (PMID 34209090, 2021). "Our study reveals that MafK is essential for LUAD tumorigenesis and is highly expressed in cancer tissue/cell lines." (PMID 37491302, 2023). "To further support these conclusions, we analyzed the cancer cell line database across all members of the NFE2:MAF family including MAFG, MAFF, MAFK, NFE2L1, and NFE2L2." (PMID 37985752, 2023). "Most of the NRF2 pathway-related genes showed extensively negative relationships with RNAss; for example, the expressions of FOS, JUN, MAF, MAFK, and PRRT2 in various cancers were negatively related to RNAss." (PMID 35242279, 2022). "In ESCC cell lines, we examined all AP-1 transcription factors including JUN, FOS, MAF, and ATF family members and found that FOSL1, MAFK, BATF, and ATF5 are upregulated compared to non-cancer cells." (PMID 34722266, 2021). "Direct comparison of FPKM distributions show us that all three transcription factors: BACH2, MAFK and NFE2L2 are downregulated in cancer cells." (PMID 33806327, 2021). "To identify direct NRF3 target genes in cancer cells, we searched ChIP sequence data for MAFF and MAFK in the ChIP-Atlas database because ChIP sequence data for NRF3 were not available and because these sMaf proteins are heterodimerization partners of NRF3." (PMID 31288376, 2019). "In this case, aging hypomethylated dmCpG sites tended to display a more marked enrichment of most of the cancer hypomethylation factors and, additionally, revealed the presence of other family‐ or function‐related proteins, like FOSL1/2, MAFF, MAFK, and STAT3." (PMID 29504244, 2018).
tumor (10 papers, 2018 to 2026). "This highlights a potential role of the NFE2L2/MAFK axis in stress adaptation, drug resistance, and tumor progression." (PMID 40806565, 2025). "Violin plots demonstrated significantly elevated activities of IRF5, IRF8, KLF2, TFAP2B, and MAFK in Zbp1−/− tumor cells, while E2F4 and ETV4 were preferentially activated in WT tumors." (PMID 41430036, 2025). "Bioinformatics analysis indicates that MafK promotes tumor invasion via the cell-substrate adhesion pathway." (PMID 37491302, 2023). "Overall, it is noteworthy that while some genes have been associated only with TNBC metastasis so far (i.e., TIEG1, MAFK, MLK3, SDPR), the majority is also involved in other tumor types, suggesting a more fundamental role in cancer progression." (PMID 29520340, 2018). "During intravasation, TGFβ promotes overexpression of musculoaponeurotic fibrosarcoma oncogene family protein K (MAFK) to induce EMT and enhance tumor formation and invasion in vivo." (PMID 29520340, 2018).
infection (2 papers, 2022 to 2023). The state of being infected such as from the introduction of a foreign agent such as serum, vaccine, antigenic substance or organism. "In this research, MafK overexpressing transgenic (MafK Tg) mice were found to be more susceptible to infection with Salmonella on the mucosa than the wild-type (WT) mice." (PMID 35260530, 2022). "Following infection by Salmonella, Caco-2 cells overexpressing MafK had much higher levels of cleaved caspase-3 compared to the results obtained from the control cells." (PMID 35260530, 2022). "TNF-α, IL-6, and INF-γ’s Levels in the serum of MafK Tg mice were all significantly upregulated compared to WT mice following a 2 day infection with Salmonella." (PMID 35260530, 2022). "JQ-1 administration induced an upregulation of MAFK, TMBIM6, and NRF-2 target proteins, with a more pronounced effect in the presence of infection." (PMID 37747932, 2023).
intestinal disease (1 paper, 2022). "Therefore, the development of MafK inhibitor can be used as a treatment strategy for intestinal disease." (PMID 35260530, 2022).
neurological disorders (1 paper, 2023). "FEV is believed to regulate genes involved in early brain development and the serotonergic pathway, and MAFK is associated with numerous neurological disorders through oxidative stress response." (PMID 37533331, 2023).
MAFK also shares sentences with these, for which no sentence is quoted: autism (1 paper); endometriosis (1); Hepatitis (1); injury (1); liver cancer (1); major depression (1); multiple myeloma (1); Multiple Organ Failure (1); non-small cell lung carcinoma (1); osteosarcoma (1); pancreatic cancer (1); pancreatic ductal adenocarcinoma (1); pancreatic neuroendocrine tumor (1); psychosis (1); testicular tumours (1); tuberculosis (1).